CLCA3P (chloride channel accessory 3, pseudogene)
Synonyms: formerly CLCA3
Gene: Transcribed unprocessed pseudogene on chromosome 1 (86,634,276 to 86,654,745, forward strand). Ensembl gene ENSG00000153923.
Diseases named in the same sentence as CLCA3P in open-access papers:
CLCA3P is named in the same sentence as 2 diseases in open-access papers, as found by Europe PMC text mining. Sharing a sentence is not in itself a finding about the gene and the disease. The quoted sentences say what the papers report.
glioma (2 papers, 2019 to 2022). A benign or malignant brain and spinal cord tumor that arises from glial cells (astrocytes, oligodendrocytes, ependymal cells). "Six pseudogenes (SP3P, ANXA2P3, PTTG3P, LPAL2, CLCA3P, and TDH) were reported to be associated with overall survival in glioma." (PMID 36333286, 2022). "A prior report that constructed another signature with six pseudogenes (SP3P, ANXA2P3, PTTG3P, LPAL2, CLCA3P, and TDH) for prediction of glioma patient survival." (PMID 31681595, 2019).
CLCA3P also shares sentences with these, for which no sentence is quoted: infection (1 paper).